INS (insulin)
Diseases named in the same sentence as INS in open-access papers (continued):
Sharing a sentence is not in itself a finding about the gene and the disease.
Obesity (continued). "This cycle of inflammation becomes self-sustaining and, over time, contributes to the reduced insulin sensitivity and metabolic dysfunction observed in patients with obesity and mouse models of obesity." (PMID 31015794, 2019). "Germ-free mice have reduced adiposity, improved tolerance to glucose and insulin and are protected from diet-induced obesity when fed a Western diet." (PMID 30866899, 2019). "Treatment with CAR agonists, in contrast, enhances insulin sensitivity, improves glucose and lipid metabolism, and reverses diet-induced obesity in rodents, reviewed in." (PMID 30792693, 2019). "We found that prenatal dexamethasone treatment enhances the susceptibility of offspring to postnatal HF diet-induced programmed obesity, insulin dysregulation, and hypertension." (PMID 30658634, 2019). "This review will focus on DNA methylation as a possible mechanism regulating, specifically, leptin and insulin signaling within the hypothalamic ARC during the pathogenesis of obesity." (PMID 31660128, 2019). "Consistent with these in vitro results, by intravenous injection of OPN-expressing adenovirus to the mice, we found OPN can delay the development of obesity and improve insulin sensitivity." (PMID 30911298, 2019). "In obesity, the insulin sensitivity of peripheral tissue is impaired because of the adipokines, soluble factors released form adipose depots." (PMID 31906216, 2019). "Recently, it has been shown to link fat cells and obesity to β-cell function, as adipsin increases insulin secretion mediated by the production of peptide complement 3a." (PMID 30998792, 2019). "For this reason, in the current study, we investigated the impact of two agents that lower plasma insulin concentrations under both fed and fasted conditions, CRMP and dapagliflozin, in two mouse models of obesity-associated cancer." (PMID 31867105, 2019). "Hyperglycaemia during pregnancy due to pre-existing or gestational diabetes mellitus leads to increased nutrient transfer to the foetus, resulting in increased birth weight and impaired glucose tolerance, insulin secretory defects and obesity in later life." (PMID 30858575, 2019). "We also show the intriguing finding that obesity blunts insulin-mediated resistance vessel relaxation and Akt phosphorylation, while IGF-1-mediated vasorelaxation and Akt phosphorylation remained intact." (PMID 30295509, 2019). "Our study demonstrates that miR-146a deficiency in mice had no influence on the development of high fat diet (HFD)-induced (i) obesity (body weight gain), (ii) adipose tissue inflammation, (iii) adipose tissue remodeling (iv) glucose and insulin tolerance." (PMID 31477775, 2019). "In summary, blueberry-supplemented diet significantly increased insulin sensitivity in HFD-induced obesity mouse model." (PMID 31139236, 2019). "Obesity increases blood insulin levels and decreases IGFBP1 concentration, resulting in a rise in IGF1 levels." (PMID 31623387, 2019). "More specifically, CB1 receptor activation can result in insulin desensitization and suppressed metabolic activity, whereas inhibition of this same receptor has been shown to attenuate such manifestations of obesity-induced metabolic syndrome." (PMID 30148676, 2019). "Several metabolic parameters (glucose, insulin, fatty acids, adipocytes, gut microbiome) are involved in the obesity pathogenesis, as well as all the systems (gastric, nervous) that regulate appetite control or food intake." (PMID 31467596, 2019). "Particular emphasis will be given to adipose tissue macrophages, crucial players of insulin resistance and chronic metabolically triggered inflammation during obesity." (PMID 31497027, 2019). "Previous studies have described the involvement of miR-221 in the development of obesity and decreased insulin sensitivity." (PMID 31828133, 2019). "Lastly, 12-HCD mice exhibited the greatest levels of obesity, hyperglycaemia, hyperinsulinemia and hyperlipidaemia together with impaired glucose- and insulin-tolerance." (PMID 30006585, 2019).
Obesity (continued). "As demonstrated in other animal models, insulin resistance precedes the development of obesity until age 20 weeks." (PMID 29497383, 2018). "Experimental studies support the link between such metabolic disturbances and AD with impaired amyloid or tau pathologies being worsened following the development of obesity and insulin-resistance in transgenic AD models of amyloidogenesis or Tau pathology." (PMID 29403354, 2018). "Subjects with obesity exhibited significantly higher weight, BMI, waist circumference, insulin and leptin concentrations compared with age-matched and gender-matched normal weight individuals." (PMID 30266914, 2018). "The impaired cross-talk between the endocrine activity of adipose tissue and other insulin-dependent organs is characteristic for obesity and metabolic syndrome." (PMID 29849871, 2018). "Obesity is accompanied by metabolic alterations characterized by insulin resistance and cardiac lipotoxicity." (PMID 29361517, 2018). "Studies indicated that the leptin is involving in the pathophysiology of obesity and there is a positive interaction between leptin and insulin." (PMID 30360409, 2018). "In established obesity, omentectomy eliminates the omental production of inhibitors of the leptin and insulin effects, particularly CRP and IL-6." (PMID 29367725, 2018). "Past research shows more deprived populations benefit more from greenspace in regards to obesity rates, mortality rates, birth outcomes, and insulin resilience levels." (PMID 30037037, 2018). "Upon a high fat diet (HFD) but not upon a low fat diet (LFD), mice expressing the mutant apoE3Leiden and CETP (E3L*CETP) develop obesity, fatty liver, and insulin resistance." (PMID 30250222, 2018). "When insulin secretion is inadequate and cannot overcome the insulin resistance occurring as a result from obesity or other factors, hyperglycemia (elevated blood sugar levels) would occur." (PMID 32232090, 2018). "Overall, our data suggest that NP signalling in human adipocytes is an important determinant of insulin sensitivity that is altered in obesity and T2D." (PMID 29348496, 2018). "Obesity and strenuous physical activity are conditions that alter the profiles of specific hormones such as insulin and adipokines and, thus, definitely impair the women fertility." (PMID 29523133, 2018). "In obesity, the insulin/Snail1 brake was impaired, likely contributing to increased hepatic lipogenesis and NAFLD." (PMID 30013137, 2018). "The hypothalamic inflammatory process that occurs in obesity impairs insulin and leptin signaling in this tissue and, consequently, can decrease WAT browning." (PMID 29643769, 2018). "For instance, patients with PHP1A have decreased insulin sensitivity that appears early during childhood, which seems to be only partially related to the degree of obesity." (PMID 29959430, 2018). "Both processes are reportedly elevated in insulin-resistant individuals with obesity compared to insulin-sensitive individuals with obesity." (PMID 29075849, 2018). "We previously found that Ahnak functions in obesity resistance and insulin sensitivity by regulation of Smad1/5 signaling pathways." (PMID 30154465, 2018). "Consistent with this, Wtap heterozygous knockout mice are protected from diet-induced obesity with smaller size and number of adipocytes, leading to improved insulin sensitivity." (PMID 29866655, 2018). "Decreased insulin-stimulated glucose transport in skeletal muscle has been shown to be a major contributing factor to IR in patients with T2D and obesity." (PMID 29552281, 2018). "Overexpression of DGAT1 in white adipose tissue of mice exposed to high-fat diet leads to increased accumulation of TAGs in adipose tissue and to obesity, but it also improves insulin sensitivity in comparison with wild-type mice." (PMID 30081476, 2018). "In other words, these models lack sufficient insulin secretion required to compensate for the insulin resistance as part of the obesity (obesity-induced hyperglycemia)." (PMID 29850600, 2018).
Obesity (continued). "Continuous administration of Glu-OC via a subcutaneous osmotic pump lowered blood glucose levels and increased pancreatic β-cell mass, insulin secretion, and insulin sensitivity in mice with high-fat diet-induced obesity." (PMID 30428526, 2018). "Comparatively little is known about how cellular immunity relates to compartmentalized, tissue‐specific inflammatory cues and insulin resistance during obesity." (PMID 30548217, 2018). "Under certain conditions, such as obesity, this process can become defective, leading to a condition known as insulin resistance." (PMID 29402381, 2018). "Our results suggest that CNP overexpression in adipocytes protects against adipocyte hypertrophy, excess lipid metabolism, inflammation, and decreased insulin sensitivity during HFD-induced obesity." (PMID 29391544, 2018). "Age, smoking, obesity, insulin, and stress can contribute to increased levels of PAI-1, suggesting a link between impaired fibrinolysis and metabolic and cardiac diseases." (PMID 30402041, 2018). "HIF-1α mRNA and protein are enhanced in adipose tissue in a model of diet-induced obesity, by a mechanism that involves adipogenesis, insulin, and hypoxia." (PMID 30443205, 2018). "The focus on one of the four classes (WHRonly−) enabled us to reveal the digestive systems as a pathway for obesity genetics that extends upon previous work highlighting neural and adiposite/insulin pathways." (PMID 29769528, 2018). "We also confirmed that D2R levels were lower in HF-fed animals, also consistent with other obesity D2R studies and D2R-dependent mechanisms of insulin and/or leptin signaling." (PMID 29698491, 2018). "The obesity-derived adipokines not only impair systemic insulin action but also increase the incidence of hepatocellular carcinoma (HCC), a highly prevalent cancer with poor prognosis." (PMID 30224299, 2018). "This obesity-driven, low-grade, chronic inflammation affects insulin sensitivity of all metabolic organs such as WAT, liver, muscle, pancreas, and even the central nervous system." (PMID 30591653, 2018). "For instance, the rescue of a reduced level of miR-181b in epithelial cells of adipose tissue in a mouse model of obesity leads to an improvement in glucose homeostasis and insulin sensitivity." (PMID 29740397, 2018). "In obesity, the infiltrated immune cells promote the production of pro-inflammatory cytokines that inhibit adipogenesis and insulin signalling." (PMID 29967467, 2018). "Obesity has been found to reduce insulin/insulin-like growth factor-1 activation and increase the levels of tumor necrosis factor-α in the brain, which then increases neural inflammation." (PMID 29673239, 2018). "Mechanistically, the anti-obesity effect of these cytokines was mediated by inhibition of IKKβ activation and endoplasmatic reticulum stress leading to restoration of central insulin and leptin sensitivity." (PMID 30158466, 2018). "Hypoxia-inducible factor-α (HIF-α) is a fundamental transcription factor involved in the oxygen homeostasis that induces inflammation and insulin resistance in obesity." (PMID 30443205, 2018). "The mechanisms by which cells become refractory to insulin action in obesity are not completely understood." (PMID 30116154, 2018). "Risk factors for progression to T2DM include family history of T2DM, need of insulin treatment, and obesity." (PMID 30186874, 2018). "Obesity is associated with reduced AMPK activation, concomitant with alterations in glycolysis, insulin sensitivity, hepatic lipid metabolism and inflammation." (PMID 30304866, 2018). "FGF21 boosts glucose uptake, decreases hepatic gluconeogenesis, increases insulin sensitivity and lessens hyperglycemia in a diet-induced mouse model of obesity." (PMID 29444136, 2018). "Individuals with obesity were evaluated and it was identified that those with a higher percentage of lean mass also had higher insulin sensitivity and lower inflammatory status." (PMID 29791653, 2018).
Obesity (continued). "IL-6 signaling in NK cells was shown to drive their reprogramming into cells with myeloid gene expression and thereby impair insulin action in obesity." (PMID 30591653, 2018). "Although we did not adjust for LGA or maternal glucose control, we observed a slight increase in the odds of overweight/obesity among offspring with exposure to maternal weight gain per kg after adjusting for maternal insulin per kg during pregnancy." (PMID 30559715, 2018). "Taking advantage of the known participation of hepatocyte toll-like receptors (TLRs) on obesity-induced hepatic metabolic alterations, inflammation, and insulin resistance, the studies also extended this knowledge." (PMID 30134638, 2018). "Reduction in the plasma level of adiponectin in subjects with obesity precedes the reduction in insulin sensitivity and onset of diabetes." (PMID 29619754, 2018). "Studies have shown that vaspin can improve glucose tolerance and insulin sensitivity in rats with diet-induced obesity and plays an important role in lowering blood glucose and reducing the insulin concentration." (PMID 30202052, 2018). "Elevated TCPTP in POMC neurons in obesity and/or after fasting repressed insulin signaling, the activation of POMC neurons by insulin and the insulin-induced and POMC-mediated repression of HGP." (PMID 30230471, 2018). "We found a high prevalence of obesity (73.7%) in the insulin-resistant group compared with the insulin-sensitive group (36.8%)." (PMID 29694633, 2018). "Subjects with overweight and obesity had higher fasting serum insulin and total cholesterol (all p < 0.05) than subjects in the normal-weight group." (PMID 29417372, 2018). "The deletion, mutation, or reduction of PTEN has several clinical implications, including insulin sensitivity and obesity." (PMID 30445764, 2018). "Disrupted central insulin signalling, particularly in the ARC, causes defects in energy homeostasis, including disrupted glucose homeostasis and obesity." (PMID 30043179, 2018). "When obesity and pregnancy act in concert as pregnancy advances, the increase in insulin resistance becomes much greater than in lean gravid individuals." (PMID 30336561, 2018). "In obesity, plasma FFAs are chronically elevated, which in muscle, can directly inhibit insulin activation of the IRS-1/PI3K/Akt pathway leading to reduced glucose uptake and phosphorylation, and decreased glycogen synthase activity." (PMID 29614722, 2018). "Irrespective, our studies point towards the heightened hypothalamic TCPTP levels in obesity resulting in the majority of POMC neurons being inhibited by insulin, to contribute to the increased HGP and fasting hyperglycemia that accompany the obese state." (PMID 30230471, 2018). "Previous work has highlighted the beneficial effects of lifestyle interventions on insulin secretion and β-cell function in adults with obesity; however, few adolescent-based studies have been conducted to date." (PMID 29471797, 2018). "The aim is to offer new insights in PCOS patients strictly selected in order to avoid confounding factors such as dyslipemia, obesity, altered glucose/insulin metabolism, cardiovascular disease, or cancer." (PMID 29435121, 2018). "Human Adv36 can induce insulin sensitivity, obesity, and hepatic steatosis in chickens, mice, and monkeys." (PMID 30400600, 2018). "In summary, our results provide new evidence for the Y1 receptor acting in a counter-regulatory fashion in insulin release in vivo and suggest that impaired Y1 receptor signaling in the pancreas may play a causal role in the development of metabolic diseases such as obesity." (PMID 30177746, 2018). "It is believed that the mechanism of increased LVM is related to microvascular disease, inflammation, obesity, elevated oxidative stress, increased insulin resistance, myocardial fibrosis, left ventricular remodeling, and other conditions." (PMID 30261876, 2018).
Obesity (continued). "In rodents, a post-weaning obesogenic diet has been reported to exacerbate the detrimental effects of maternal diet-induced obesity on offspring body weight gain, lipid metabolism, insulin sensitivity, and endothelial dysfunction." (PMID 29635288, 2018). "IKKβ/NF-κB, as a mediator of metabolic inflammation, is a new strategy to combat obesity and its related diseases via regulating central insulin/leptin signaling and action." (PMID 29930535, 2018). "We previously found in obese women that skeletal muscle seems to be the primary tissular target of insulin signaling defects in obesity development." (PMID 29849911, 2018). "In line with this, inhibition of ATGL in mice using Atglistatin leads to improvement of insulin signalling and a reduction of diet-induced obesity and hepatosteatosis, likely due to a reduced release of adipose tissue-derived FAs in the circulation." (PMID 30081476, 2018). "They found that TGR5–Akt–mTOR signaling pathway was important in improving insulin action and modulating chemokine expression in obesity-induced insulin-resistant models." (PMID 30486474, 2018). "On the other hand, several studies revealed that a global decrease of the IIS leads to obesity, as seen, for example, in the Ilp2-3,5 triple mutants, and in the flies with ablation of the insulin-producing median neurosecretory cells." (PMID 29954158, 2018). "In obesity adipose cells fail to respond to insulin and glucose transport and lipid regulation are impaired." (PMID 29292863, 2018). "The discovery of ATMs, and their elevated numbers in the adipose tissues of obese mice and humans, indicates mechanisms by which obesity induces adipose inflammation and systemic insulin resistance." (PMID 29674655, 2018). "While insulin's vasodilator actions predominate in normal conditions, insulin's vasoconstrictor effect is dominant in obesity and DM2, as a result of increased ET-1 production and decreased NO production." (PMID 29628894, 2018). "Exercise can also increase insulin and its downstream protein expressions in the myocardium of diet-induced obesity rats, as well as forkhead box protein o1 (Foxo1) and other key regulators of pancreatic β cells, and also activate insulin signaling pathway." (PMID 30559720, 2018). "Beiging of WAT not only enhances energy expenditure, but also improves glucose metabolism, insulin sensitivity, and hyperlipidemia to ameliorate obesity and its related cardiometabolic complications." (PMID 30423881, 2018). "When comparing to children who are in a normal weight range, obesity affects blood pressure and blood lipid concentrations and increases insulin resistance; however, children in a normal weight range can also present metabolic alterations." (PMID 29402762, 2018). "Tamoxifen-inducible β-cell-targeted Swell1 KO mice have normal fasting serum glucose and insulin levels but impaired glucose-stimulated insulin secretion and glucose tolerance; and this is further exacerbated in mild obesity." (PMID 29371604, 2018). "Some studies have suggested that obesity decreases satellite cell activation, anabolic signaling, insulin sensitivity, and 5′-AMP-activated protein kinase (AMPK) activity, which are required for muscular regeneration." (PMID 29966377, 2018). "In our study, the group with obesity showed higher values with statistical significance in fasting glucose, fasting insulin, HOMA-IR, and HOMA-IR > 3.16, with respect to their controls at any stage of pubertal development." (PMID 30254673, 2018). "Of course, maternal overweight/obesity and increased gestational weight gain play an important detrimental role, just due to tight links with glucose metabolism (insulin sensitivity)." (PMID 29925339, 2018). "It has also been reported that TRO can prevent obesity by improving insulin signaling pathway, and it returns blood glucose, fatty acids, and cholesterol levels to the normal levels." (PMID 30140406, 2018).